KLK8 (kallikrein related peptidase 8)
Diseases named in the same sentence as KLK8 in open-access papers (continued):
Sharing a sentence is not in itself a finding about the gene and the disease.
infection (6 papers, 2016 to 2025). The state of being infected such as from the introduction of a foreign agent such as serum, vaccine, antigenic substance or organism. "Infection of BV2 mouse microglial cells with increasing concentrations of KLK8 adenovirus (Ad-KLK8) resulted in a corresponding augmentation in the mRNA and protein expression levels of KLK8 and Iba1." (PMID 40521191, 2025). "Infection of HT22 cells or primary isolated neonatal neurons with increasing concentrations of KLK8 adenovirus (Ad-KLK8) led to an increase in KLK8 expression in a dose-dependent manner." (PMID 37076499, 2023). "Infection of HCAECs with increasing concentrations of KLK8 adenovirus (Ad-KLK8) led to an increase in KLK8 expression in a dose-dependent manner." (PMID 33754057, 2021). "The present study found that Ad-KLK8 infection resulted in a 2.88 ± 0.35 fold increase in the content of bradykinin in the culture medium of HCAECs." (PMID 33754057, 2021). "We found that infection of cardiomyocytes with KLK8 adenovirus resulted in a 3.56 ± 0.58 fold increase in the content of bradykinin in culture media." (PMID 26823023, 2016). "In addition, secreted trypsin-like serine protease kallikrein-8 (KLK8) has been shown to cleave the L1 capsid, independently of cyclophilin B, and this also causes a structural change in the capsid to promote infection." (PMID 30181457, 2018). "Infection of cardiomyocytes with KLK8 adenovirus resulted in KLK8 overexpression." (PMID 26823023, 2016).
psychiatric disorder (4 papers, 2020 to 2025). A disorder characterized by behavioral and/or psychological abnormalities, often accompanied by physical symptoms. "Tissue kallikrein-related peptidase 8 (KLK8), a trypsin-like serine protease, has been implicated in the pathogenesis of several psychiatric disorders." (PMID 37076499, 2023). "KLK8 is also known to cleave the extracellular portion of several membrane proteins, including synaptic adhesion molecule L1, neuregulin-1, and ephrin type-B receptor 2, which has been implicated in the pathogenesis of psychiatric disorders." (PMID 37076499, 2023). "Here, we review data on regulation of the neuropsin gene KLK8 in the context of mental health and provide a summary of clinical and preclinical evidence supporting a role for neuropsin in the pathogenesis of mental illness." (PMID 32414324, 2020). "Through systematic interrogation of large-scale genetic data, we review KLK8 regulation in the context of mental health and provide a summary of clinical and preclinical evidence supporting a role for neuropsin in the pathogenesis of mental illness." (PMID 32414324, 2020). "Through systematic interrogation of available large-scale genetic and post-mortem brain transcriptomic studies, we do not find compelling clinical data that support KLK8 dysregulation in mental illness." (PMID 32414324, 2020).
KLK8 also shares sentences with these, for which no sentence is quoted: lung squamous cell carcinoma (3 papers); metastatic tumors (3); metastatic melanoma (2); pancreatic adenocarcinoma (2); Thyroid carcinoma (2); attention deficit-hyperactivity disorder (1); benign tumors (1); brain cancer (1); brain diseases (1); cardiomyopathy (1); chromophobe renal cell carcinoma (1); dilated cardiomyopathy (1); disc degeneration (1); glioblastoma (1); hepatocellular carcinoma (1); Hyperkeratosis (1); hypotrichosis (1); ichthyosis (1); intracranial hemorrhage (1); leukemia (1); Lung Injury (1); lymph node metastasis (1); memory impairment (1); neurological disorders (1); non-small cell lung carcinoma (1); oral squamous cell carcinoma (1); papillary renal cell carcinoma (1); peeling skin syndrome (1); postpartum depression (1); psoriatic arthritis (1).
A further 7 diseases each share a sentence with KLK8 in 1 paper.